REN (renin)
Diseases named in the same sentence as REN in open-access papers (continued):
Sharing a sentence is not in itself a finding about the gene and the disease.
Hypertension (continued). "Previous studies on hypertension have mainly focused on the periphery, in which inflammatory response, renin-angiotensin-aldosterone system, non-coding RNA influence, macrophage polarization, etc may cause hypertension." (PMID 34938159, 2021). "The renin–angiotensin system plays a vital role in the regulation of hypertension." (PMID 34771631, 2021). "To date, aliskiren is the only one renin inhibitor approved for treating hypertension." (PMID 33669059, 2021). "These include an enhanced expression of the angiotensin converting enzyme 2 (ACE2), diabetes-related microvascular dysfunction, increased expression of pro-inflammatory cytokines, or activation of the renin-angiotensin-aldosterone system related to hypertension." (PMID 33841339, 2021). "The decreased Cx37 expression in yotari medulla might contribute to hypertension reduction provoked by high renin expression." (PMID 33525532, 2021). "This indicates that high-flow AVF is associated with increased natriuretic peptides and hormones of the renin-angiotensin-aldosterone system, that may balance each other regarding fluid retention and hypertension and support remaining kidney function." (PMID 34605197, 2021). "In this context, it would be interesting to examine its influence in rats with renin–angiotensin–aldosterone system-dependent hypertension, in which a cannabinoid CB1 receptor antagonist has been shown to decrease blood pressure, in contrast to the increase in SHR." (PMID 34063297, 2021). "Although the mechanism of interaction between ELABELA and the renin-angiotensin system is still not well known, ELABELA inhibits the renin-angiotensin system and may become a novel therapeutic target for hypertension and AF." (PMID 34384364, 2021). "This may represent the continuum of renin-independent aldosteronism which also contains subjects with mild-to-moderate hypertension." (PMID 34054559, 2021). "Although the renin–angiotensin–aldosterone (RAA) system is key in the pathophysiology of hypertension, there is no convincing evidence it plays a major role in VEGFI-associated hypertension." (PMID 33404052, 2021). "In conclusion, these results support the hypothesis that the activation of the potentially protective arm of the renin-angiotensin-system could be a new therapeutic strategy to counteract myocardial organ damage in arterial hypertension." (PMID 34948475, 2021). "Renin–Angiotensin–Aldosterone System Inhibitors, commonly used to treat hypertension, have a role in ACE2 homeostasis and it is possible that a modification in quantity and site of ACE2 expression could modify susceptibility and disease outcome." (PMID 33626045, 2021). "Indeed, endothelial dysfunction and an increased expression of ICAM-1 play roles in the initiation of the inflammatory process, which in turn has been reported to affect the renin-angiotensin system and contribute to hypertension." (PMID 34444896, 2021). "Primary aldosteronism (PA) is characterized by inappropriate aldosterone production leading to renin suppression, which, if prolonged and severe, may in turn lead to hypertension and hypokalemia." (PMID 33912136, 2021). "These guidelines served to increase awareness of hypertension; encourage proper antihypertensive medication usage, such as medications blocking the renin-angiotensin system; and lifestyle modification, such as adherence to the Dietary Approaches to Stop Hypertension (DASH) recommendations." (PMID 34371815, 2021). "Furthermore, there is a strong evidence to support the role of VDD in the activation of renin–angiotensin system (RAS) that leads to hypertension." (PMID 34456872, 2021). "Thus, clinical trials designed to answer how to best manage patients with low renin hypertension and cardiac history are greatly needed." (PMID 33841329, 2021). "Pathophysiologic mechanisms of hypertension among African Americans may involve the intra-renal renin-angiotensin system, variations in angiotensinogen, and increased aldosterone sensitivity." (PMID 34589710, 2021).
Hypertension (continued). "The cause of this potential dedifferentiation might be the disturbance of Cx40 intercellular signaling that leads to a disbalance of blood pressure control through renin secretion and hypertension onset." (PMID 33525532, 2021). "The renin–angiotensin system (RAS) and renin–angiotensin–aldosterone system (RAAS) are enzymatic pathways that contribute to the progression of cardiovascular disease (CVD) and CVD events and participate in CVD risk factors, e.g., hypertension." (PMID 34357323, 2021). "Therefore, we decided to examine the role of the interaction between hypertension and the renin-angiotensin system in the pathophysiology of myocardial I/R injury." (PMID 34122103, 2021). "Dysregulation of sympathetic nervous and renin-angiotensin systems resulting in enhanced stimulation of both adrenergic and angiotensin II receptors is a typical feature of heart failure and hypertension and is involved in the pathogenesis of insulin resistance." (PMID 34220710, 2021). "In this regard, vitamin D receptor knockout mice develop severe hypertension and, conversely, vitamin D receptor agonists (VDRAs) such as paricalcitol lower blood pressure in conjunction with inhibitors of the renin-angiotensin-aldosterone system (RAAS) in experimental CKD." (PMID 34821697, 2021). "Thus, blocking the effect of the renin-angiotensin system would have a beneficial role in the management of hypertension." (PMID 34452161, 2021). "Obesity-related hypertension could be due to multiple mechanisms including, endothelial dysfunction, renal affection, stimulation of the renin–angiotensin–aldosterone system (RAAS), and insulin resistance." (PMID 33761942, 2021). "Moreover, specific adipokines secreted from adipocytes enhance the endothelial vasomotor tone by activating the renal renin-angiotensin system, which increases hypertension in obese patients." (PMID 34769060, 2021). "Hypertension is a complicated multifactorial disease attributable to dysregulation of angiogenesis and vascular smooth muscle, myocardial hypertrophy, activation of the renin-angiotensin-aldosterone system and platelet functional impairment." (PMID 34495077, 2021). "Until large prospective longitudinal studies of patients with PA and other low-renin hypertension will elucidate the optimal parameters for guiding medical therapy titration, incorporating renin targets within PA practice guidelines is likely to benefit patient care." (PMID 33841329, 2021). "While we considered the top 10 pathways common between hypertension and COVID-19 using these common 13 and f4-gene sets, we observed that the renin-angiotensin system, metabolism of angiotensinogen to angiotensin, and peptide hormone metabolism pathways were the top pathways for these shared genes." (PMID 34067609, 2021). "We therefore concluded that understanding the impact of broad-spectrum antibiotics on gut microbiota and knowing its non-microbial effects on gut barrier and vascular wall can significantly help guide appropriate treatment strategies for patients with low renin hypertension." (PMID 34578849, 2021). "However, the hypertension is also of neurogenic origin, apparently dependent on activation of the brain renin-angiotensin system (RAS)." (PMID 33651165, 2021). "This suggests an overactivation of intrarenal RAAS, and the increased synthesis of AII in the kidney that is so far compensating hypertension, in contrast to the stenotic one, may also be triggered by the renin-independent mechanism." (PMID 33799957, 2021). "Shear stress in hypertension may induce endothelial dysfunction, impair renal autoregulation, change renal blood flow, activate the renin-angiotensin-aldosterone system (RAAS), and result in CKD." (PMID 34867799, 2021). "In this study, we determined whether B1R mediates kidney injury in a low renin, salt- sensitive model of hypertension." (PMID 35118089, 2021).
Hypertension (continued). "The underlying biological mechanisms may be explained as a high-fat-diet-induced sensitization of angiotensin-II-elicited hypertension is mediated by leptin through the upregulation of the central renin–angiotensin system and proinflammatory cytokines." (PMID 34886102, 2021). "The renin-angiotensin-aldosterone system (RAS) is crucial in the development of hypertension and organ damage, and the activation of brain RAS has been revealed to aggravate the cognitive decline and dopaminergic neuron loss by promoting oxidative stress and inflammation processes." (PMID 33485385, 2021). "Finally, calcitriol reduction of miR106b-5p release to the circulation by pro-inflammatory monocyte-macrophages provides the first causal link between macrophage ER stress activation and the induction of renin-dependent hypertension." (PMID 34950686, 2021). "For example, the systemic renin-angiotensin system is activated in hypertension secondary to renal artery stenosis, and activation of Gq-coupled cardiac receptors by circulating AngII would be expected to play an important role in the induction of LVH in this situation." (PMID 33659256, 2021). "Severe vitamin D deficiency, commonly observed in COVID-19 hospitalized patients and in obese subjects may directly promote hypertension and impact on the renin–angiotensin system components that could contribute to target organ damage." (PMID 33804084, 2021). "Therefore, the crosstalk between hypertension and COVID-19 is mediated by the renin-angiotensin system." (PMID 34067609, 2021). "When the hypertension is long lasting, plasma renin activity decreases." (PMID 34638148, 2021). "Medications for hypertension such as inhibitors of the renin-angiotensin system or calcium channel blockers may also decrease cfPWV, while beta-blockers and diuretics would have minimal impact, if any, on AS." (PMID 34441912, 2021). "Inhibitors of the renin-angiotensin system (RAS) are widely used to treat hypertension." (PMID 34762601, 2021). "The renin activity in patients with ARA of the diagnosed hypertension group (2.19 ± 2.91) was higher compared to patients with ARA of undiagnosed hypertension group (1.43 ± 2.07) and also higher than patients with NAR of diagnosed hypertension group (1.75 ± 2.85) (p < 0.001, both)." (PMID 35003315, 2021). "Moreover, the advantages of losing weight in overweight patients with IgAN with protein and sodium restriction and maximal control of hypertension using treatment with inhibitors of the renin-angiotensin system were confirmed." (PMID 34659212, 2021). "Our analysis also found that the renin-angiotensin system is shared by hypertension and COVID-19." (PMID 34067609, 2021). "The blockade of the renin–angiotensin–aldosterone system (RAAS) by angiotensin-converting enzyme inhibitors (ACEIs) or angiotensin receptor blockers (ARBs) is one of the most common treatments for hypertension, heart failure and renal diseases." (PMID 33231730, 2021). "roots, known as shirin bayan in ITM, contain glycyrrhizic and glycyrrhetinic acids that possess mineralocorticoid activity and can cause hypokalemia, sodium and water retention, metabolic alkalosis, hypertension, and suppression of the renin-aldosterone system." (PMID 34795786, 2021). "In light of these findings, an abnormally large 1-year expansion in plasma volume may result from renin angiotensin aldosterone system activation due to a reduction in plasma volume, hypertension, dyslipidemia, diabetes mellitus, and smoking." (PMID 34255808, 2021). "The potential mechanism in the management of hypertension through the inhibition of ACE involves the control of the production of nitric oxide (NO) by the regulatory mechanism of the renin-angiotensin-aldosterone system (RAAS) with ACE inhibition as a fundamental regulator of blood pressure." (PMID 35011441, 2021).
Hypertension (continued). "Increased angiotensinogen levels led to the suspicion that obese rats developed hypertension with the involvement of the renin–angiotensin system, and this could contribute to the overgrowth of cardiomyocytes." (PMID 33716957, 2021). "AME is a rare disease per se although it was hypothesized that a mild reduction of 11β-HSD2 activity can have a role also in low renin essential hypertension (EH)." (PMID 34497581, 2021). "The renin-angiotensin system (RAS) is best known for its modulation of essential hypertension." (PMID 34697992, 2021). "Based on a study on Cx40 –/– mice, Cx40 might be connected to renin release and renin-dependent hypertension." (PMID 33172216, 2020). "In the same model used in this work, ANG II infusion (25 ng/min, 14 days) display hypertension and kidney injury, thus indicating that changes in CD-renin may impact intrarenal Ang II formation contributing to the development of hypertension." (PMID 33281610, 2020). "A detailed understanding of the mechanisms by which macrophage ER stress causes miR-106b-5p secretion will direct the development of specific therapies preventing the miRNA-mediated activation of multiple signaling pathways and transcription factors involved in renin-dependent hypertension." (PMID 32968066, 2020). "The establishment of impaired renal function in cnnm2a mutants leads to the obvious question of whether the functions of renin or aldosterone, which are the key regulators of hypertension via the RAAS pathway, are altered in this model." (PMID 32984406, 2020). "Low-renin status in therapy-resistant hypertension: a clue to efficient treatment." (PMID 32267335, 2020). "Hypertension was reported to be the most common presenting symptom (90%) which is thought to occur secondary to altered blood flow due to kinking or twisting of the renal artery with subsequent increased renin secretion induced hypertension." (PMID 33057847, 2020). "A hyperactive brain renin-angiotensin system, oxidative stress and neuroinflammation in brainstem cardiovascular centres and other brain regions increase sympathetic activity in hypertension." (PMID 32470081, 2020). "Under prolonged hypertension and high aldosterone levels, decreased eGFR may also stimulate the synthesis and secretion of renin in PA patients." (PMID 32089681, 2020). "Uric acid can increase the expression of renin, then change the hemodynamics of glomerular filtration through angiotensin II, inducing systemic hypertension and glomerular hypertension as well as renal interstitial tubular injury, finally resulting in glomerular sclerosis and interstitial fibrosis." (PMID 32701116, 2020). "Our results are consistent with Folkow’s hypotheses that not only pharmacological (renin–angiotensin system) but also various vascular mechanisms participate in the development of hypertension." (PMID 33076449, 2020). "Renin-angiotensin system inhibitors (ACEI) can improve LA strain in patients with hypertension." (PMID 32326882, 2020). "Renin-angiotensin system (RAS) plays an important role in the pathogenesis of hypertension." (PMID 32641121, 2020). "Hypertension may depend on multiple factors; among them it is relevant to cite the activation of the renin-angiotensin system mainly by renin overexpression secondary to low vitamin D, the decreased activity of eNOS and the decreased levels of GSH." (PMID 32708578, 2020). "In hypertension, there is insulin resistance and activation of the sympathetic nervous system and renin–angiotensin–aldosterone system, which may result in diffuse myocardial fibrosis." (PMID 32998742, 2020). "While hypertension is associated with COVID-19 morbidity, it is not independent of age; thus further study is needed to elucidate the extent to which hypertension and/or dysregulation of the renin–angiotensin–aldosterone system (RAAS) contribute to COVID-19 pathogenesis." (PMID 34192044, 2020).
Hypertension (continued). "Furthermore, renal sympathetic nerves contribute to hypertension by means of sodium retention, stimulation of renin secretion, and augmentation of sympathetic activity induced by the central nervous system." (PMID 31939995, 2020). "The impact of NO bioavailability on intracellular renin accumulation in M-1 cell cultures may explain animal models of hypertension." (PMID 33281610, 2020). "In contrast, our experiments showed that Nam had no BP-lowering effects in severe hypertension caused by an unregulated overproduction of renin in mice." (PMID 32905409, 2020). "However, excessive licorice use is known to cause pseudohyperaldosteronism, which is characterized by sodium retention, hypertension, hypokalemia, metabolic alkalosis, and suppression of the renin-angiotension-aldosterone system." (PMID 32791684, 2020). "Considering renin's drug set predictions' enriched diseases, two of them are “cardiovascular diseases” and “vascular diseases”, two generic disease groups, where one of the members is hypertension." (PMID 33209251, 2020). "Loss of ERRα expression, whether stimulated by high sodium, low potassium, or high renin, leads to hypotension instead of hypertension." (PMID 33553162, 2020). "Moreover, in the only study reporting the prevalence of renin-angiotensin system inhibitors use, ~30% of patients reported prevalent hypertension, but only ~5% of patients were taking renin-angiotensin system inhibitors." (PMID 33150129, 2020). "His hypertension in this stage might be due to kidney and renin-angiotensin-aldosterone system dysfunction." (PMID 32243412, 2020). "Such physiological alterations due to high SUA levels could contribute to the activation of the renin-angiotensin system and endothelial dysfunction, which could eventually lead to AF in hypertension patients." (PMID 33330657, 2020). "To examine the role of the lymphatic vasculature in cardiac dysfunction further, we used a model of angiotensin II infusion, which promotes cardiac dysfunction directly via its effects on cardiomyocytes and indirectly by its action on the renin-angiotensin system to induce hypertension." (PMID 33200983, 2020). "In patients on dialysis, the principal mechanism of hypertension has been thought to be sodium and volume excess, among other factors, such as arterial stiffness, activation of the renin–angiotensin–aldosterone and sympathetic nervous systems, and endothelial dysfunction." (PMID 33379300, 2020). "This experimental renovascular hypertension model is used widely to delineate the relationship among the renin-angiotensin system and hypertension and its local and systemic changes and test the effect of therapeutic drugs in the treatment of chronic hypertension." (PMID 33145109, 2020). "Recent research conducted with mice without the Vdrgene (which codes for the vitamin D receptor) and the Cyp27B1 gene (which codes for alpha-1-hydroxylase) demonstrated thatthese animals had high levels of renin and, consequently, of angiotensin II,provoking hypertension and cardiac hypertrophy." (PMID 34178073, 2020). "Thus, we propose that decreased NO bioavailability, as seen in many forms of chronic kidney diseases, induces intrarenal RAS activation by stimulating CD-renin production, resulting in increased sodium reabsorption, hypertension, and kidney injury." (PMID 33281610, 2020). "The pancreatic stellate cell is important and may reflect the activation of the peri-islet pericytes in the Ren2 model of lean hypertension with excess renin and Ang II." (PMID 33202960, 2020). "Moreover, in wild-type recipient mice of KODMAC/miR106b−/− bone marrow, knockout of miR-106b-5p prevents the hypertension and JG cell renin production induced by KODMAC macrophages, suggesting myeloid-specific, miR-106b-5p-dependent effects." (PMID 32968066, 2020). "Myeloid cells are involved in hypertension, but their exact role in renin-induced hypertension remains unclear." (PMID 32968066, 2020).